LINC01070 (long independently transcribed non-coding RNA 1070)
Gene: Long non-coding RNA gene on chromosome 13 (112,189,089 to 112,201,007, forward strand). Ensembl gene ENSG00000260102.
Diseases named in the same sentence as LINC01070 in open-access papers:
LINC01070 is named in the same sentence as 1 disease in open-access papers, as found by Europe PMC text mining. Sharing a sentence is not in itself a finding about the gene and the disease. The quoted sentences say what the papers report.
breast carcinoma (1 paper, 2024). "Furthermore, clone formation assay, EdU assay, and Transwell assay showed that knockdown of LINC01070 inhibited breast cancer progression." (PMID 38860098, 2024).